KRTAP2-2 (keratin associated protein 2-2)
Description:
In the hair cortex, hair keratin intermediate filaments are embedded in an interfilamentous matrix, consisting of hair keratin-associated proteins (KRTAP), which are essential for the formation of a rigid and resistant hair shaft through their extensive disulfide bond cross-linking with abundant cysteine residues of hair keratins. The matrix proteins include the high-sulfur and high-glycine-tyrosine keratins (By similarity).
Synonyms: KAP2.2; KAP2.1; KRTAP2-1; KRTAP2.1A; KRTAP2.1B
Tractability: No criterion of Open Targets' tractability assessment is met for any kind of drug.
Gene: Protein-coding gene on chromosome 17 (41,054,498 to 41,055,230, reverse strand). Ensembl gene ENSG00000214518.
Pathways (Reactome):
Developmental Biology: Keratinization
Gene Ontology:
Cellular component: cytosol; keratin filament
Genetic constraint (gnomAD): Loss-of-function variants: 1 observed, 0.86 expected, observed/expected ratio (o/e) 1.17, 90% interval 0.28 to 1.9. That is too few expected variants to judge how well the gene tolerates losing a copy. Missense variants: 4 observed, 17.75 expected, observed/expected ratio (o/e) 0.23, 90% interval 0.11 to 0.52. Synonymous variants: 0 observed, 8.15 expected, observed/expected ratio (o/e) 0, 90% interval 0 to 0.37.
Homologues: Orthologues: mouse Krtap5-24 (42% identical), mouse Krtap5-2 (37% identical), mouse Krtap5-26 (36% identical), rat Krtap5-8 (34% identical), rat AABR07006049.1 (33% identical), mouse Krtap5-20 (32% identical). Paralogues in human: KRTAP2-1 (100% identical), KRTAP2-3 (99% identical), KRTAP2-4 (99% identical), KRTAP4-12 (51% identical), KRTAP4-3 (50% identical), KRTAP4-6 (50% identical), KRTAP4-11 (49% identical), KRTAP4-5 (49% identical), KRTAP4-9 (47% identical), KRTAP9-1 (46% identical), KRTAP4-4 (45% identical), KRTAP9-2 (44% identical), and 35 more.